RNU6-740P (RNA, U6 small nuclear 740, pseudogene)
Gene: Small nuclear RNA gene on chromosome 10 (90,922,731 to 90,922,835, reverse strand). Ensembl gene ENSG00000201604.
Homologues: Orthologues: chimpanzee U6 (97% identical), macaque U6 (91% identical), pig U6 (81% identical), dog U6 (79% identical), guinea pig U6 (79% identical), rabbit U6 (73% identical), rabbit U6 (68% identical), mouse Gm54605 (67% identical), rat LOC120101208 (67% identical). Paralogues in human: RNU6-1251P (85% identical), RNU6-1020P (84% identical), RNU6-1078P (84% identical), RNU6-12P (84% identical), RNU6-13P (84% identical), RNU6-16P (84% identical), RNU6-32P (84% identical), RNU6-33P (84% identical), RNU6-41P (84% identical), RNU6-42P (84% identical), RNU6-456P (84% identical), RNU6-959P (84% identical), and 1285 more.